APOE (apolipoprotein E)
Diseases named in the same sentence as APOE in open-access papers (continued):
Sharing a sentence is not in itself a finding about the gene and the disease.
Alzheimer disease (continued). "Endotoxin binds directly to APOE, and the APOE4 variant both sensitises to endotoxin and predisposes to Alzheimer’s disease." (PMID 31519175, 2019). "While a stronger role of the APOE than TOMM40 variants in Alzheimer's disease was suggested, comparative contribution of the TOMM40‐APOE variants in the regulation of body weight remains elusive." (PMID 30462377, 2019). "Apolipoprotein E (APOE) ε4 allele is so far the only established genetic factor for sporadic Alzheimer’s disease." (PMID 31214016, 2019). "We also observed evidence of colocalization for several genes at the APOE locus that were associated with Alzheimer’s disease." (PMID 30820025, 2019). "The E4 allele of APOE (E4) is the strongest genetic risk factor for the development of late onset Alzheimer’s disease (AD)." (PMID 30791549, 2019). "Allele-specific distinctions in the human apolipoprotein E (APOE) locus represent the best-characterized genetic predictor of Alzheimer's disease (AD) risk." (PMID 30683808, 2019). "With APOE harboring the largest genetic risk factors for Alzheimer’s disease, it is important to properly characterize the entire gene." (PMID 31104630, 2019). "These individuals have a higher risk of developing Alzheimer’s disease than do those with ApoE ε3 polymorphism, the most common form." (PMID 31675964, 2019). "In this regard, a meta-analysis found increased odds of developing Alzheimer’s disease based on the presence of herpes virus type 1 and Epstein-Barr virus DNA in the brain, a risk further increased in APOE ε4 carriers." (PMID 31194855, 2019). "Apolipoprotein E (ApoE) allele, considered a major genetic risk factor for Alzheimer disease and a possible confounding factor in the association between periodontitis and dementia." (PMID 31560644, 2019). "For interest, we also found that APOE—the top genetic risk for Alzheimer’s disease —is approximately 6% dark CDS (by depth) for certain ADSP samples with whole-genome sequencing, and the same region is dark in gnomAD whole-exome data." (PMID 31104630, 2019). "Apolipoprotein E (ApoE) is the strongest known common genetic risk factor for Alzheimer's disease (AD)." (PMID 30949567, 2019). "Apolipoprotein E (apoE) is linked to the risk for Alzheimer’s disease (AD) and thus has been suggested to be an important therapeutic target." (PMID 30934555, 2019). "The APOE gene influences the human brain and is one of the significant genetic factors associated with the development of Alzheimer’s disease, which is also associated with a cognitive performance." (PMID 31100889, 2019). "The strongest genetic risk factor for Alzheimer's disease (AD) is the Apolipoprotein E type 4 allele (ApoE ε4)." (PMID 31410194, 2019). "Humans have three common apoE isoforms, apoE2, apoE3 and apoE4, that show a strong genotype effect on the risk and age of onset for sporadic and late onset forms of Alzheimer’s disease (AD)." (PMID 31052389, 2019). "This study describes a gauge for brain aging predictive of cognitive decline and Alzheimer's disease synergistic with the APOE ε4 allele." (PMID 31133613, 2019). "Associations between cardiometabolic risk factors and PRS for Alzheimer’s disease (including the ApoE region) atp≤5×10-8." (PMID 31984241, 2019). "One such example is the APOE locus, a well-established risk factor associated with altered probability of sporadic Alzheimer's disease onset." (PMID 31428784, 2019). "The APOE-ε4 allele has long been associated with increased risks of Alzheimer's disease and mortality, but the effect of the less prevalent APOE-ε2 allele on diseases in the elderly and survival remains elusive." (PMID 31356640, 2019). "One specific genetic factor, Apolipoprotein E ε4 (ApoE ε4) not only increases the risk for developing Alzheimer’s Disease and vascular dementia but also puts healthy individuals at risk of a faster cognitive decline as they age." (PMID 31077187, 2019).
Alzheimer disease (continued). "Apolipoprotein E (APOE) is the most recognizable genetic risk factor for late-onset Alzheimer’s disease (AD)." (PMID 30983990, 2019). "The purpose of this study was to investigate the poorly explored amyloidogenic properties of human apolipoprotein E, a protein closely associated with disorders with worldwide prevalence, such as Alzheimer’s disease." (PMID 31071995, 2019). "The first-ranked gene FMR1 was proved to be associated with mental diseases like mental retardation and autism, and five other genes (APP, SNCA, MAPT, SIRT2, APOE) are known to be associated to Alzheimer's disease." (PMID 32038710, 2019). "Although increasing age is a strong risk factor for Alzheimer’s disease, sex and genetic factors such as APOE ε4 status are also associated with Alzheimer’s disease." (PMID 31194855, 2019). "Studies investigating the relationship between apoE and cerebrovascular function are needed to increase our understanding of the role of this protein in vascular dysfunction associated with Alzheimer’s disease." (PMID 31052389, 2019). "ApoE genotype has the most profound genetic risk on late onset Alzheimer’s disease and also affects processes in normal brains." (PMID 31788012, 2019). "The LDL receptor has a high affinity to apoE which in humans exists in three isoforms: apoE2, apoE3, and apoE4, the latter being a major risk factor for cardiovascular diseases and Alzheimer's disease." (PMID 31485289, 2019). "High-risk populations are defined as individuals with a family history of Alzheimer’s disease, the ε4 allele of the APOE gene, or the presence of biomarkers, like elevated τ and a high Aβ1-42/Aβ1-40 ratio." (PMID 31221862, 2019). "Regardless of the differences between cohorts, the presented results support the previous SNP finding that the APOE ε4 gene is the main risk factor for Late Onset Alzheimer’s disease." (PMID 31842725, 2019). "Three genes downregulated during hibernation (PS1, PS2, and APOE) are linked to early onset Alzheimer’s disease." (PMID 31170930, 2019). "Education, sex, and the APOE-rs405509 variant are associated with Alzheimer’s disease and cognitive performance." (PMID 31100889, 2019). "Previous studies have shown the dose dependent role of apolipoprotein E (ApoE) ε4 allele as a risk factor for developing Alzheimer's disease, increasing the risk of AD by 2.6 to 14.9 fold and lowering the onset by 7 to 15 years." (PMID 30991617, 2019). "In particular, the T allele of the rs405509 single nucleotide polymorphism (SNP) located on the promoter of the APOE gene is a well-established variant associated with Alzheimer’s disease and cognitive performance." (PMID 31100889, 2019). "The nuclear hub network enrichment was driven by genes implicated in Alzheimer’s disease (APOE), non-alcoholic drug-related phenotypes (RAB4B-EGLN2), and cognitive ability (LRRN2 and MAPT)." (PMID 31171808, 2019). "The risk of Alzheimer’s disease increases with increasing number of the ε4 allele, although the risky effect of APOE ε4 allele tends to decrease with advancing age." (PMID 31214016, 2019). "The association of APOE ε4 with Alzheimer's disease remained significant at the exome-wide level after adjustment with PC1–3 (Padj-PC = 1.95 × 10−7, ORadj-PC = 3.20)." (PMID 31032141, 2019). "We studied resting-state oscillatory connectivity using magnetoencephalography in healthy young humans (N = 183) genotyped for APOE-ɛ4, the greatest genetic risk for Alzheimer’s disease (AD)." (PMID 31038453, 2019). "The onset age of Alzheimer’s disease is decreased by about 3–4 years for people who carry every APOE ε4 allele." (PMID 31214016, 2019). "A well-established susceptibility genetic factor for Alzheimer’s disease is the apolipoprotein E (APOE) ε4 allele." (PMID 30984391, 2019). "This study also suggests that the alteration of the olfactory system by oestradiol treatment is amplified by the presence of apolipoprotein E, a genetic risk factor for Alzheimer’s disease." (PMID 31882785, 2019).
Alzheimer disease (continued). "Taken together, these considerations reflect the established role of APOE in risk for Alzheimer’s disease/CAA by dint of their role in Aβ aggregation, deposition and clearance." (PMID 32954261, 2019). "Variants in the apolipoprotein E (APOE) gene play an important role in the development of Alzheimer’s disease (AD)." (PMID 32226373, 2019). "This is in line with the meta-analysis suggesting that APOE ε4 allele is associated with a moderately increased risk for progression from MCI to Alzheimer dementia." (PMID 31214016, 2019). "Among these types of lipoproteins, apolipoprotein E has received much attention due to the relationship of particular alleles of its gene with the risk and progression of Alzheimer's disease." (PMID 31787919, 2019). "It has been reported that TREM2 binds to apolipoproteins including APOE, which is the strongest genetic risk factor for late-onset Alzheimer disease." (PMID 31649511, 2019). "The other was the missense APOE variant, a proxy for the ε4 allele known to predispose to Alzheimer’s disease and responsible for the association signal with the number of nocturnal sleep episodes." (PMID 30952852, 2019). "Apolipoprotein E4 (APOE4) and ageing are the most important known risk factors for late-onset Alzheimer’s disease (AD)." (PMID 30700991, 2019). "The Alzheimer’s disease risk allele at the APOE locus had apparently paradoxical associations with sleep related traits." (PMID 30952852, 2019). "For example, the possession of the e4 allele of the gene for Apolipoprotein E (APOE) is associated with an increased risk of developing Alzheimer’s disease." (PMID 30071465, 2019). "Specifically, we demonstrate that TREE enables for the enrichment of cells that had been edited at the APOE(R158) locus, a gene associated with altered risk of Alzheimer's disease onset." (PMID 31428784, 2019). "The ε4 allele of the apolipoprotein ε (APOE) was associated with an earlier onset of Alzheimer’s disease." (PMID 30642023, 2019). "ApoE4 is the strongest known genetic risk factor for Alzheimer’s disease, however, the contributions of apoE to pathology associated with AD are still unclear." (PMID 31052389, 2019). "Using this approach, we have probed the interaction between amyloid-β fibrils, associated to Alzheimer’s disease, and apolipoprotein E, a well-known ligand frequently found co-deposited to the fibrillar form of Aβ in vivo." (PMID 31829176, 2019). "Effect sizes for PAM measures are substantial, comparable to that of APOE ε4, the strongest genetic risk factor for Alzheimer’s disease, and mediation models support an upstream role for microglial activation in Alzheimer’s disease via accumulation of tau." (PMID 30679421, 2019). "Studies have shown that the ε4 variant of APOE is associated with an increased risk for Alzheimer’s disease (AD), and approximately 40% of AD patients carry at least one ε4 allele." (PMID 30700058, 2019). "Apolipoprotein E (APOE) is the predominant lipoprotein in the brain and is the strongest genetic risk factor for Alzheimer’s disease (AD)." (PMID 31022959, 2019). "Apolipoprotein E (APOE) genotype determines Alzheimer's disease (AD) susceptibility, with the APOE ε4 allele being an established risk factor for late‐onset AD." (PMID 31058310, 2019). "Apolipoprotein E (APOE) is the most established gene associated with the pathogenesis of late-onset Alzheimer’s disease (AD)." (PMID 31831047, 2019). "The apolipoprotein E (APOE) gene is the strongest genetic risk factor for late-onset Alzheimer disease (AD)." (PMID 31623648, 2019). "Advanced age and the APOE ε4 allele are the two biggest risk factors for Alzheimer’s disease (AD) and declining cognitive function." (PMID 31133613, 2019). "The allele epsilon 4 (ε4) of apolipoprotein E (ApoE) is the strongest genetic risk factor for Alzheimer’s disease (AD)." (PMID 31717561, 2019).
Alzheimer disease (continued). "APOE E4 is the major genetic risk factor for Alzheimer's disease (AD), increasing risk and decreasing age of disease onset, and a lot of research has demonstrated the detrimental effects of APOE E4 in varying cellular contexts." (PMID 31866940, 2019). "Such genetic effect is characterized in the hippocampus atrophy with the apolipoprotein E, ε4 allele (ApoE-ε4), which is also associated with an increased risk for developing late onset Alzheimer’s disease (AD)." (PMID 30519892, 2019). "Apolipoprotein E (ApoE) is the most important genetic risk factor for Alzheimer's disease (AD), with ApoE4 thought to enhance and accelerate amyloid-β (Aβ) pathology." (PMID 30949567, 2019). "Apolipoprotein E (APOE) e4 is the major genetic risk factor for late-onset Alzheimer's disease (AD)." (PMID 30852398, 2019). "Rare partial loss-of-function mutations in the TREM2 gene are associated with an increase in the risk of Alzheimer’s disease dementia, comparable to that associated with the APOE ɛ4 allele." (PMID 30239611, 2018). "The APOE ε4 allele is the minor allele in modern humans and is a major genetic risk factor for Alzheimer’s disease." (PMID 30412599, 2018). "Most notably, HSV-1 infection has been linked to Alzheimer’s disease and to the expression of the apolipoprotein 4 (APOE-ε4) allele isoform." (PMID 30167845, 2018). "In terms of genetic influence on age-related brain changes, perhaps the most widely studied contributor of age-related brain changes is apolipoprotein E (apoE) E4, a well-established Alzheimer's disease susceptibility gene." (PMID 29452862, 2018). "The translocase of outer mitochondrial membrane 40 (TOMM40), which lies in linkage disequilibrium with the apolipoprotein E (APOE) gene, has been implicated in Alzheimer’s disease (AD)." (PMID 30517207, 2018). "APOE ε4 allele is most common genetic risk factor for Alzheimer’s disease (AD) and cognitive decline." (PMID 29745836, 2018). "The role of cholesterol in lipid raft maintenance has been cited as a likely explanation for observations that high cholesterol and APOE-ε4 genotype are the major risk factors for Alzheimer’s disease." (PMID 29954063, 2018). "In the central nervous system, while apoE is the major cholesterol transport protein, a dysfunction of apoE in the transport and metabolism of lipids is associated with Alzheimer’s disease." (PMID 29933361, 2018). "The ɛ4 allele of the apolipoprotein E gene (APOE4) is the strongest known common genetic risk factor for sporadic late-onset Alzheimer’s disease." (PMID 29860282, 2018). "Polymorphic alleles in the apolipoprotein E (APOE) gene are the main genetic determinants of late-onset Alzheimer's disease (AD) risk." (PMID 30618606, 2018). "Epidemiology studies have indicated an association of apolipoprotein E (ApoE) genetic polymorphism and circulating steroid hormone levels with the risk of Alzheimer’s disease." (PMID 29559956, 2018). "APOE has also a major role in brain lipid metabolism, and the APOE ε4 isoform is a well-established risk factor for Alzheimer’s disease." (PMID 30019023, 2018). "Our study showed that the risk of Alzheimer disease is lower for individuals who inherited the genomic region surrounding the ApoE gene from an African ancestor than it is for risk allele carriers who inherited the region from a European ancestor." (PMID 30517106, 2018). "Apolipoprotein E (apoE) is a forefront actor in the transport of lipids and the maintenance of cholesterol homeostasis, and is also strongly implicated in Alzheimer’s disease." (PMID 29933361, 2018). "The Mirage study showed a significant decrease in the risk of Alzheimer’s disease among statin users even after adjusting for race and APOE genotype." (PMID 29507718, 2018). "Statin use was associated with significantly reduced risk of incident Alzheimer’s disease after adjustment for age, gender, education, and APOE genotype." (PMID 29507718, 2018).
Alzheimer disease (continued). "The risk for Alzheimer’s disease (AD) is associated with the presence of the ε4 allele of Apolipoprotein E (APOE) gene and, recently, with a novel genetic variant of the RNF219 gene." (PMID 29755337, 2018). "This APOE allele is known to be associated with a decrease in the hippocampal volume, both in individuals with mild cognitive impairment and in Alzheimer’s disease." (PMID 30390165, 2018). "Variants of APOE (APOE4) is known as the strongest risk factor for late onset Alzheimer’s disease and has also been suggested to have a proinflammatory effect on microglia." (PMID 29807527, 2018). "Apolipoprotein E4 (ApoE4) is the strongest genetic risk factor for late onset Alzheimer’s Disease (AD), and is associated with impairments in cerebral metabolism and cerebrovascular function." (PMID 29962946, 2018). "The ε4 allele of the apolipoprotein E gene (APOE-ε4) is the strongest genetic factor for late-onset Alzheimer’s disease." (PMID 29793545, 2018). "The most important risk locus for LOAD remains on the long arm of chromosome 19 containing the APOE locus, which was the first, and is the strongest, risk factor for Alzheimer’s disease (AD)." (PMID 29872490, 2018). "The apolipoprotein E (APOE) gene on chromosome 19q13.32, was the first, and remains the strongest, genetic risk factor for Alzheimer’s disease (AD)." (PMID 29872490, 2018). "Vascular pathology and genetic markers such as apolipoprotein E allele ε4 (ApoE ε4) are risk factors for the progression from mild cognitive impairment (MCI) to Alzheimer's disease (AD)." (PMID 32341958, 2018). "On the other hand, LDL receptor causes clearance of apolipoprotein-E, a protein responsible for Alzheimer's disease." (PMID 29770231, 2018). "Compared with those individuals with an APOE ε3/ε3 genotype, white individuals with one copy of the ε4 allele show an increased lifetime risk of developing Alzheimer's disease (AD) (ε2/ε4, OR 2.6; ε3/ε4, OR 3.2)." (PMID 29793545, 2018). "Meanwhile, the patient displayed the APOE ε3/ε4 genotype, which confers an increased risk of developing Alzheimer's disease (AD)." (PMID 29467647, 2018). "We found that higher tau pathology in the right entorhinal cortex was associated with greater loneliness, controlling for age, sex, and apolipoprotein E ε4, the Alzheimer’s disease genetic risk marker." (PMID 30563962, 2018). "Apolipoprotein E (APOE) ε4 allele is the strongest genetic risk factor for late-onset Alzheimer’s disease mainly by modulating amyloid-β pathology." (PMID 30348994, 2018). "These associations remained after adjustment for the APOE genotype, as well as in an analysis restricted to ε33 carriers for Alzheimer’s disease." (PMID 29534716, 2018). "ApoE, a protein best known for its link to Alzheimer’s disease, is one of the most robustly synthesized candidates at the initial stage of axon growth, and one of the ApoE 5’UTR splice variants harbors a CERT-like motif." (PMID 29756027, 2018). "The APOE ε4 allele has also been associated with enhanced risk and accelerated decline in cognitive function secondary to Alzheimer’s disease in women as compared to men." (PMID 30412599, 2018). "Studies have found that APOE gene polymorphisms are closely associated with coronary heart disease, hyperlipidemia, cerebral infarction, Alzheimer’s disease, multiple sclerosis, chronic hepatitis, and other diseases." (PMID 30508003, 2018). "Even within early-onset Alzheimer’s disease, significant variability in phenotype, pathology, and disease duration exists, modified by mutations and variables such as apolipoprotein E(APOE) status." (PMID 30567585, 2018). "For example, we found Alzheimer’s Disease risk genes APOE, PLD3, TREM2, UNC5C, AKAP9, and ADAM10 in our orthologous gene list." (PMID 30382841, 2018). "Multifactorially adjusted hazard ratios for Alzheimer’s disease and all dementia were 2.72 (2.45–3.01) and 2.21 (2.05–2.38) for the APOE ɛ4 allele." (PMID 29534716, 2018).